MIR941-1 (microRNA 941-1)
Synonyms: hsa-mir-941-1; MIRN941-1; mir-941-1
Gene: MicroRNA gene on chromosome 20 (63,919,449 to 63,919,520, forward strand). Ensembl gene ENSG00000283206.
Diseases named in the same sentence as MIR941-1 in open-access papers:
MIR941-1 is named in the same sentence as 1 disease in open-access papers, as found by Europe PMC text mining. Sharing a sentence is not in itself a finding about the gene and the disease.
MIR941-1 shares sentences with these, for which no sentence is quoted: viral infection (1 paper).